LDHA (lactate dehydrogenase A)
Diseases named in the same sentence as LDHA in open-access papers (continued):
Sharing a sentence is not in itself a finding about the gene and the disease.
endometrial cancer (5 papers, 2018 to 2025). Primary or metastatic malignant neoplasm involving the endometrium (mucous membrane that lines the endometrial cavity). "Although LDHA shows diagnostic potential for endometrial carcinoma, current in vitro evidence is inadequate to support its clinical reliability as a novel biomarker." (PMID 41561760, 2025). "LDHA exhibits overexpression in both tumor tissues and cell lines in endometrial carcinoma, serving as a potential biomarker for accurately distinguishing normal endometrium from carcinoma." (PMID 41561760, 2025). "This study identified 28 differentially expressed proteins in endometrial cancer samples, with LDHA, PKM, MMP9, NAMPT, and SPIT1 showing the best performance in distinguishing endometrial cancer from normal tissues." (PMID 39194522, 2024). "Overexpression of CTSB, CALU, S100A6, LDHA, and HNRNPA1 in endometrial cancer tissues was validated by WB, and IHC showed an intense cytoplasmic and nuclear staining of S100A6 in tumor samples." (PMID 39194522, 2024). "Among 52 proteins previously identified by the research team, 8 proteins (MMP9, KPYM, LDHA, CADH1, NAMPT, MPO, ENOA and CAPG) achieved the highest accuracy in diagnosing endometrial cancer in CVF." (PMID 39194522, 2024). "Lactate dehydrogenase A (LDHA) has been confirmed as a tumor promoter in various cancers, but its role in endometrial cancer remains unclear." (PMID 39582531, 2024).
endometriosis (5 papers, 2022 to 2024). The growth of functional endometrial tissue in anatomic sites outside the uterine body. "LDHA has also been implicated in the progression and prognosis of endometriosis." (PMID 38744310, 2024). "In contrast to the normal endometrial and eutopic endometrium, our investigation demonstrated increased expression of ALDOA, PKM2, and LDHA in ectopic endometriosis." (PMID 38744310, 2024). "In conclusion, we show that the higher expression of LDHA induces higher levels of lactate in endometriosis." (PMID 37945340, 2023). "We first indicated that the higher levels of lactate, and LDHA enhanced the H3K18lac in ectopic endometrial tissues and eESCs, and that lactate promoted cell proliferation, migration, and invasion in vitro in endometriosis." (PMID 37945340, 2023). "Glucose transporter 1 (GLUT1), lactate dehydrogenase A (LDHA), and pyruvate dehydrogenase kinase 1 (PDK1) have been suggested as key enzymes for maintaining glycolytic metabolism in endometriosis." (PMID 35444541, 2022). "Moreover, although we elucidated the notable anti-endometriosis effects of PV, the mode-of-action (MOA) of a single compound contained in PV-antagonized LDHA activity is unclear." (PMID 35444541, 2022). "In addition, several studies have shown that targeting LDHA or PDK1 might be an effective non-hormonal strategy for the treatment of endometriosis by reducing cell survival and inducing apoptotic cell death." (PMID 35444541, 2022).
head and neck squamous cell carcinoma (5 papers, 2016 to 2025). A squamous cell carcinoma that arises from any of the following anatomic sites: lip and oral cavity, nasal cavity, paranasal sinuses, pharynx, larynx, and salivary glands. "It was reported that the high levels of lactate and LDHA are associated with poor response to radiation treatments in head and neck squamous cell carcinoma (HNSCC)." (PMID 27708237, 2016). "LDHA expression levels in tumor tissues of head and neck squamous cell carcinoma (HNSCC) patients were significantly higher than healthy tissue, and associated with a poor disease-free survival." (PMID 37661238, 2023). "Another study found that cetuximab inhibited glycolysis in cetuximab-sensitive head and neck squamous cell carcinoma (HNSCC) cells by down-regulating the expression of HIF-1α and suppressing the expression of the downstream target gene lactate dehydrogenase A (LDH-A)." (PMID 36139386, 2022).
Insulin resistance (5 papers, 2016 to 2024). Increased resistance towards insulin, that is, diminished effectiveness of insulin in reducing blood glucose levels. "To explore the effect of insulin resistance on glycolysis, we detected the expression of key glycolytic enzymes (HK2, PKM2, and LDHA) in KGN cells after insulin treatment and RES intervention." (PMID 36742000, 2022). "The results showed that HOMA-IR was negatively correlated with HK2, LDHA, PKM2, SIRT2, and lactic acid levels and had little correlation after RES intervention, which indicated that RES intervention promoted glycolysis by improving ovarian insulin resistance in PCOS rats." (PMID 36742000, 2022).
primary hyperoxaluria (5 papers, 2021 to 2024). A hereditary disorder characterized by excessive oxalate production, leading to hyperoxaluria. "Nedosiran is an N-acetyl-D-galactosamine (GalNAc)–conjugated RNA interference agent targeting hepatic lactate dehydrogenase (encoded by the LDHA gene), the putative enzyme mediating the final step of oxalate production in all three genetic subtypes of primary hyperoxaluria (PH)." (PMID 37118061, 2023). "The inhibition of the hLDHA (human lactate dehydrogenase A) enzyme has been demonstrated to be of great importance in the treatment of cancer and other diseases, such as primary hyperoxalurias." (PMID 39273691, 2024). "Human lactate dehydrogenase A (hLDHA) is a homotetrameric isozyme involved in the conversion of glyoxylate into oxalate in the cytosol of liver cells (hepatocytes) and partially responsible for the overproduction of oxalate in patients with the rare disease called primary hyperoxaluria (PH)." (PMID 39769031, 2024).
type 2 diabetes (5 papers, 2015 to 2024). "The results showed that LDHA is enriched in type II diabetes mellitus, rheumatoid arthritis, ribosome, RNA degradation, valine, leucine and isoleucine degradation, fat digestion and absorption, and circadian rhythm." (PMID 39044840, 2024). "HIF target gene mRNAs for LDHA (encoding lactate dehydrogenase A), PDK1 (encoding pyruvate dehydrogenase kinase isoform 1) and GBE1 (encoding glycogen-branching enzyme 1) were induced similarly in response to roxadustat in myotubes when comparing the NGT and type 2 diabetes groups." (PMID 38814443, 2024). "mRNAs for LDHA, PDK1 and GBE1 were induced to a similar degree in myotubes from donors with NGT or type 2 diabetes." (PMID 38814443, 2024).
viral infection (5 papers, 2021 to 2025). "However, viral infection in NK cell-specific lactate dehydrogenase A (LDHA) knockout mice is exacerbated, highlighting the critical role of aerobic glycolysis in antiviral immunity." (PMID 40498022, 2025). "Lactate reduction by inactivation of lactate dehydrogenase A (LDHA), a classical hypoxia-inducible gene, increases type I IFN production to protect mice from viral infection." (PMID 39601573, 2025). "Limiting lactate production, for instance at low glucose levels or upon inhibition of lactate dehydrogenase A (LDHA), increases the IFN response to viral infection." (PMID 34386501, 2021).
asthma (4 papers, 2022 to 2026). "But sTSLP decreased LDHA (lactate dehydrogenase A) and LD (Lactic acid) levels in BALF, and HIF-1α and LDHA protein levels in airway epithelial cells of asthma mice model." (PMID 35351157, 2022). "In this present study, airway epithelial cells LDHA and HIF-1α expression in asthmatic mice, and lactate dehydrogenase and lactic acid in alveolar lavage fluid were found obviously downregulated in asthma mice with sTSLP treatment." (PMID 35351157, 2022).
Cerebral ischemia (4 papers, 2020 to 2025). Restriction of arterial blood supply to the brain associated with insufficient oxygenation to support the metabolic requirements of the tissue. "And it has neuroprotective effects by inhibiting HIF-1α/LDHA-mediated inflammatory response after cerebral ischemia/reperfusion injury." (PMID 36467061, 2022). "Consequently, arginine inhibits inflammatory response in microglia by inhibiting HIF-1α/LDHA signaling after cerebral ischemia insult." (PMID 32321555, 2020). "To test whether the arginine/HIF-1α/LDHA pathway is neuroprotective after cerebral ischemia injury, we carried out TTC test." (PMID 32321555, 2020). "Together, these results indicate a possibility that arginine-induced neuroprotective effect may be through the suppression of HIF-1α/LDHA-mediated inflammatory response in microglia after cerebral ischemia injury." (PMID 32321555, 2020). "Furthermore, lactate dehydrogenase A (LDHA) could regulate the expression of HMGB1 by histone lactylation in cerebral ischemia/reperfusion injury." (PMID 37945340, 2023).
Ewing sarcoma (4 papers, 2020 to 2022). A small round cell tumor that lacks morphologic, immunohistochemical, and electron microscopic evidence of neuroectodermal differentiation. "The genetic depletion of lactate dehydrogenase A (LDHA) inhibits the proliferation of Ewing sarcoma cells, induces apoptosis, and reduces tumour growth." (PMID 35656815, 2022). "As an analogue of pyruvate, oxamate inhibits LDHA by competing with substrates and overcomes cetuximab resistance in Ewing’s sarcoma." (PMID 34540667, 2021). "Fu's study revealed that cetuximab (CTX)-resistant Ewing's sarcoma cells displayed upregulated LDHA expression and accelerated glycolysis." (PMID 32038983, 2020). "In the experiment, Ewing's sarcoma was re-sensitized to CTX by knocking down LDHA or inhibiting LDHA with oxalate to reduce the glycolysis rate of drug-resistant cells." (PMID 32038983, 2020).
glaucoma (4 papers, 2016 to 2024). Increased pressure in the eyeball due to obstruction of the outflow of aqueous humor. "Finally, a series of enzymes, such as lactate dehydrogenase A or monoamine oxidase B, were also identified as predicted new targets for the management of glaucoma." (PMID 39458974, 2024).
head and neck cancer (4 papers, 2021 to 2025). A primary or metastatic malignant neoplasm affecting the head and neck. "Lactate dehydrogenase A (LDHA) inhibitors demonstrate restored CTL infiltration in head and neck cancer models, particularly when combined with anti-CSF1R to deplete protumor macrophages." (PMID 40253354, 2025).
lung squamous cell carcinoma (4 papers, 2021 to 2025). "Lung squamous cell carcinoma (LUSC) represents a glycolysis‐predominant subtype, characterized by high expression levels of glucose transporter 1 (GLUT1), hexokinase 2 (HK2), and lactate dehydrogenase A (LDHA), as well as strong FDG uptake on PET imaging." (PMID 41163383, 2025).
medulloblastoma (4 papers, 2018 to 2023). A malignant, invasive embryonal neoplasm arising from the cerebellum. "The effects of LDHA inhibition by oxamate or LDHA siRNA on medulloblastoma cell line metabolism, migration and proliferation were examined." (PMID 29601482, 2018). "Additionally, the expression of lactate dehydrogenase A (LDHA) positively correlated with MYC expression levels indicative of an unfavourable prognosis in this medulloblastoma subtype." (PMID 34445233, 2021). "LDHA expression was examined in medulloblastoma subgroups and cell lines." (PMID 29601482, 2018). "We hypothesised that LDHA inhibition would result in a decrease in lactate concentrations and a change from a glycolytic to an oxidative phosphorylation metabolic phenotype, leading to decreased medulloblastoma, proliferation and motility." (PMID 29601482, 2018). "We established that aerobic glycolysis is a potential therapeutic target for medulloblastoma, but broader LDH inhibition (LDHA, B, and C) may be more appropriate than LDHA inhibition alone." (PMID 29601482, 2018). "Studies indicate MBs have a glycolytic phenotype; however, LDHA has not yet been explored as a therapeutic target for medulloblastoma." (PMID 29601482, 2018). "Furthermore, we found that oxamate significantly attenuated glycolysis, proliferation and motility in medulloblastoma cell lines, but LDHA siRNA did not." (PMID 29601482, 2018).
preeclampsia (4 papers, 2013 to 2025). Preeclampsia is a hypertensive disorder of pregnancy that is characterized by new-onset hypertension with proteinuria presenting after 20 weeks of gestation, and depending on mild or severe forms may initially present with severe headache, visual disturbances, and hyperreflexia. "Among them, fibronectin 1 (FN1), a marker of vascular injury previously reported to be elevated in preeclamptic patients, and lactate dehydrogenase A (LDHA), whose serum levels have been suggested as a marker of preeclampsia and disease severity." (PMID 41446579, 2025). "In summary, our study identified MKNK1, ARNT, FLT1, SERPINE1, ENO3, LDHA, BCL2 out of HIF1-signaling pathway as novel diagnostic biomarkers for preeclampsia patients, and a diagnostic signature based on these genes is constructed for preeclampsia." (PMID 37020283, 2023). "Seven genes (including MKNK1, ARNT, FLT1, SERPINE1, ENO3, LDHA, BCL2) were screen out to build potential diagnostic model of preeclampsia." (PMID 37020283, 2023). "However, the contribution of ENO3 and LDHA to preeclampsia is still unclear." (PMID 37020283, 2023).
astrocytomas (3 papers, 2020 to 2025). "Astrocytomas, for instance, exhibited elevated levels of glycolysis-related proteins such as hexokinase 2, lactate dehydrogenase A (LDHA), and glucose-6-phosphate dehydrogenase compared to oligodendrogliomas." (PMID 39996200, 2025).
B cell lymphoma (3 papers, 2020 to 2024). "Our findings indicate that the expression of aurora kinases and the key proteins PKM2 and LDHA were significantly elevated in B-cell lymphoma tissues." (PMID 38099309, 2023).
cervical squamous cell carcinoma (3 papers, 2021 to 2024). A squamous cell carcinoma arising from the cervical epithelium. "The expression of several glycolysis-related enzymes and proteins such as HK II, PKM2 and MCT1 increased in cervical squamous cell carcinoma, and the expression of LDHA, HK II and PKM2 increased, to some extent, in cervical precancerous lesions." (PMID 33532002, 2021).
chondrosarcoma (3 papers, 2021 to 2022). A malignant cartilaginous matrix-producing mesenchymal neoplasm arising from the bone and soft tissue. "A cell line exposed to the LDHA inhibitor oxamate can overcome doxorubicin-resistance in chondrosarcoma." (PMID 34938658, 2021). "While a prior study showed elevated LDHA activity in chondrosarcomas, our data shows that genotype alters the level of lactate, and as such genotype should be taken into account when considering strategies to target this pathway." (PMID 33762012, 2021). "Given the high activity of LDHA and glycolysis in chondrosarcoma cells, LDHA may be a therapeutic target in chondrosarcoma." (PMID 34938658, 2021).
depression (3 papers, 2020 to 2023). "It will be interesting to test the higher susceptibility of LDHA-deficient mice in developing depression symptoms when being treated with sub-threshold stress." (PMID 36759610, 2023). "By using an unbiased proteomic analysis, genetic modification, and electrophysiological recordings, we demonstrate that reduced LDHA expression underlies the compromised glycolysis and decreased neuronal excitability under a depression state." (PMID 36759610, 2023). "The mRNA expression levels of LDHA gene increased in major depressive disorder patients in both depressive state and remissive state in comparison with healthy control subjects." (PMID 32830860, 2020).
diffuse large B-cell lymphoma (3 papers, 2022 to 2025). "LDHA is highly expressed in diffuse large B-cell lymphoma (DLBC) and regulates the metabolism, proliferation and invasion of Raji cells via FER." (PMID 40165895, 2025). "Results demonstrate that Aurora A, Aurora B, and the Warburg effect-related genes LDHA (lactate dehydrogenase A) and PKM (pyruvate kinase M) were significantly overexpressed in tissues obtained from patients with diffuse large B-cell lymphoma (DLBCL) as compared to normal controls." (PMID 38099309, 2023).
epilepsy (3 papers, 2025). A brain disorder characterized by episodes of abnormally increased neuronal discharge resulting in transient episodes of sensory or motor neurological dysfunction, or psychic dysfunction. "Stiripentol, an inhibitor of lactate dehydrogenase A, was used in epilepsy management to markedly decrease the lactate levels and lead to the reverse chemoresistance." (PMID 41502520, 2025).
gastric adenocarcinoma (3 papers, 2020 to 2022). "Results showed that this cotreatment modulated numerous critical proteins, such as EGFR/HER2/HER3, Kras/ERK/Vimentin, and mTOR/HIF1-α/HK2/LDHA pathways of gastric adenocarcinoma AGS cells." (PMID 36145507, 2022).
Glycogen storage disease (3 papers, 2022 to 2025). "Overall, the main difference in the lactate stress test results of patients with LDHA deficiency compared with those with the very common glycogenosis (i.e., GSD V) is the high response of pyruvate, as the lactate response is similar in both diseases." (PMID 36292720, 2022).
Granuloma (3 papers, 2021 to 2026). A compact, organized collection of mature mononuclear phagocytes, which may be but is not necessarily accompanied by accessory features such as necrosis. "Lastly, in established, necrotic granulomas, LDHA staining is limited to the granulation layer and proximal regions of granulomatous inflammation." (PMID 37673914, 2023). "In early necrotizing granulomas, we observed intense, homogenous LDHA staining of the necrotic core, representing LDHA released from necrotic immune cells." (PMID 37673914, 2023). "The distinct patterned responses within the spectrum of lesions were illustrated by myeloid, bronchial epithelial cells, and lymphocytes that stain positive for LDHA while engaging in distinctive immunological phenomena like granuloma formation and alveolitis." (PMID 37673914, 2023). "Following Mtb infection, increased levels of both lactate and LDHA have been detected in murine lungs, and LDHA was expressed by recruited macrophages within granulomas of C3HeB/FeJ Kramnik mice." (PMID 34745105, 2021). "In non-necrotizing granulomas (NNGs), we observed clusters of LDHA-positive cells with a lower nucleus:cytoplasm ratio, likely macrophages, and some lymphocytes, spread throughout a predominantly lymphocytic infiltrate (yellow arrows)." (PMID 37673914, 2023). "We found that 7 of the top 10 unique marker genes associated with the activated neutrophils were significantly upregulated in LN granuloma compared with noninfected LN controls, as well as the pro-inflammatory markers CEBPD and LDHA." (PMID 41489684, 2026).
hereditary leiomyomatosis (3 papers, 2010 to 2022). "Furthermore, inhibition of LDHA activity resulted in reduced tumor growth in hereditary leiomyomatosis and renal cell carcinoma syndromes." (PMID 35936690, 2022).
invasive breast carcinoma (3 papers, 2017 to 2025). A carcinoma that infiltrates the breast parenchyma. "In particular, quantification of the expression of EPO, ETS1, PGK1, TPI, LDHA and ENO1 in a primary tumor sample provides information on the risk of recurrence for patients with early-stage invasive breast cancer." (PMID 28430808, 2017). "In patients with invasive breast cancer, ErbB2 is positively correlated with the HSF1/LDHA axis." (PMID 40593465, 2025).
ischemic stroke (3 papers, 2023 to 2025). A stroke disorder caused by obstruction of blood flow to the brain, due to thrombotic (local blood clot formation) or embolic (due to a blood clot or other material traveling from another site) event. "In our study LDHA levels were slightly downregulated, while previous clinical evidence associates elevated lactate dehydrogenase levels with poor prognosis in ischemic stroke patients, likely reflecting anaerobic glycolysis and tissue damage." (PMID 41342963, 2025). "Methods and Results: Pharmacological inhibition of lactate production by either inhibiting LDHA or glycolysis markedly attenuated the mouse brain injury of ischemic stroke." (PMID 39113798, 2024).